IL6 (interleukin 6)
Diseases named in the same sentence as IL6 in open-access papers (continued):
Sharing a sentence is not in itself a finding about the gene and the disease.
Sepsis (continued). "It was found that miR-19b-3p level was negatively associated with serum levels of both IL-6 (r = − 0.852, P < 0.001) and TNF-α (r = − 0.761, P < 0.001), revealing that miR-19b-3p might be associated with inflammatory responses for sepsis patients." (PMID 32188465, 2020). "MEG3 restrained the activation of TNF-α and IL-6, in sepsis models." (PMID 32410866, 2020). "Furthermore, increased levels of IL-6, BUN, and CK were associated with the development of SARS-CoV-2 infection-induced sepsis, indicating that an uncontrolled inflammatory response and multiple organ dysfunction were major characteristics for viral sepsis." (PMID 33178716, 2020). "In conclusion, it seems that IL-6 may be a useful diagnostic and prognostic marker of SIRS/sepsis in children." (PMID 32655314, 2020). "We observed that ADAR1 significantly increased the expression of suppressor of cytokine signaling 3 (SOCS3) in macrophages and reduced the expression of interleukin-6 in macrophages and the serum, thereby reducing intestinal permeability and mucosal injury in mice with sepsis." (PMID 32273831, 2020). "The present study showed that treatment with rSj-Cys significantly reduced the level of TNF-α and IL-6 in sera (systematic) and their mRNAs in cardiac homogenate (local), suggesting the regulatory effects of rSj-Cys on local (cardiac) and systematic (sepsis) immune system." (PMID 32423469, 2020). "In addition, TQ acted by reducing sepsis-induced increase in the expression of inflammatory signals including that of IL-1-β, IL-6, and TNF-α in the kidney tissue." (PMID 32626733, 2020). "IL-6 was said to be useful in predicting sepsis, with an AUC of 0.706." (PMID 32164268, 2020). "In our study, LPS was able to promote IL-6 and IL-1β production in rat sepsis model." (PMID 29984678, 2020). "During sepsis, statins affect the production of IL-6, IL-8, TNF, MCP-1, and C-reactive protein." (PMID 33110395, 2020). "Alternatively, the use of STAT3 inhibitors, such as stattic, in sepsis treatment might unmask IL-6-mediated but STAT3-independent unexpected harmful reactions." (PMID 32943679, 2020). "It has been further shown in fish that IL-6 is induced in macrophages during sepsis, and suggested that this may concur to reduce iron availability by induction of hepcidin, as a means to limit the spread of infection." (PMID 32116802, 2020). "The sepsis patients were selected based on the fulfilment of a number of criteria indicative of immune suppression, namely the number of days following the onset of sepsis, monocytic HLA-DR expression, lymphocyte profiles, IL-6 and IL-10 levels, bacterial cultures and clinical scores." (PMID 33336293, 2020). "The study revealed that IL-6 could be used to discriminate the sepsis from the control group and could also distinguish septic shock from sepsis." (PMID 33198109, 2020). "In human sepsis, IL-6 expression was correlated with organ injury and apoptosis." (PMID 32766286, 2020). "Similarly, the median concentration of IL-6 among clinical sepsis group was significantly higher than that of the control group (p < 0.001)." (PMID 33233806, 2020). "Additionally, miR-146, which was also upregulated in CMV has been shown to increase IL-6 expression by promoting the “NFκB” pathway in an in-vitro sepsis model." (PMID 32537679, 2020). "Potentially, variations in TNF-α and IL-6 protein expression in samples from sepsis patients after LPS challenge may be explained by when blood samples were taken in relation to the different phases of sepsis." (PMID 33382782, 2020). "Moreover, eicosanoid levels in paws correlated positively with systemic IL-6 concentrations, suggesting interdependencies between immunologically relevant mediators during aggravated sepsis." (PMID 33117382, 2020).
Sepsis (continued). "Moreover, the serum level of IL-6 is <4 pg/mL in healthy individuals, but it increases to >1000 pg/mL in severe sepsis, which indicated that IL-6 can serve as an excellent biomarker of severity and prognostic indicator of outcome for septic patients." (PMID 32197507, 2020). "The normal physiological range of IL-6 is 5–25 pg/mL, whereas in patients with sepsis, it may rapidly increase to 1,000 pg/mL." (PMID 32273831, 2020). "IL-6 has pivotal role in manifestation of many diseases, including cancer and sepsis." (PMID 31979357, 2020). "TNF is able to inhibit viral replication and respond to sepsis via IL-1- and IL-6-producing cells." (PMID 33067513, 2020). "The relative levels of IL-6 were positively associated with those of IL-8, MCP-1, and PAI-1 (r = 0.6164, P < 0.0001; r = 0.5717, P = 0.0003; and r = 0.3823, P = 0.0234, respectively) in the sera of sepsis patients." (PMID 32826331, 2020). "In this regard, it is, however, likely that Il6 during sepsis in realiter can be present longer and attain higher concentrations, because normally more than 1 h elapses until the patient appears in the clinic with the diagnosis of sepsis." (PMID 33178198, 2020). "IL-6 takes part into acute-phase response, and it is an important biomarker of sepsis severity." (PMID 33110395, 2020). "Also, prior studies observed that serum IL‐6 and IL‐10 levels were remarkably up‐regulated in patients with sepsis." (PMID 32383354, 2020). "The role of IL-6 in detecting sepsis, therefore, remains inconclusive." (PMID 33198109, 2020). "The levels of serum TNF-α, IL-1β, and IL-6 were increased significantly in rats in the sepsis group compared to rats in the sham group 24 h after surgery (P < 0.01), while TNF-α, IL-1β, and IL-6 concentrations at 24 h after CLP were reduced after NRG-1β treatment (P < 0.01)." (PMID 32765805, 2020). "Intraperitoneal administration of 5-MTP to LPS-induced sepsis model results in suppression of macrophage activation and cytokine expression accompanied by reduction of serum cytokines (IL-6, IL-1β, TNFα and IFNγ) and chemokines (CXCL-1, MCP-1, Rantes and Eotaxin)." (PMID 32635910, 2020). "SST could relieve the injury, the decrease of SSTRs, and the increase of TNF-α and IL-6 induced by sepsis and also further enhanced the expression of IL-10." (PMID 33376482, 2020). "IL-6 is an important proinflammatory cytokine involved in sepsis." (PMID 32451375, 2020). "Among neonates with proven sepsis, the optimal cut-off value of IL-6 was 313.5 pg/mL." (PMID 33233806, 2020). "In the non-clinical study, RJX exhibited potent and dose-dependent protective activity, decreased the inflammatory cytokine responses (interleukin-6, tumor necrosis factor alpha, transforming growth factor beta), and improved survival in the LPS-GalN mouse model of sepsis and ARDS." (PMID 33244300, 2020). "Finally, sepsis increased IL-6 mRNA only in the ALA group (+278% compared to the sham-operated group with the ALA substitution)." (PMID 32365668, 2020). "Post-transcriptional modulation of IL-6 has been strongly related to the pathogenesis of sepsis." (PMID 33182754, 2020). "Comparisons of cytokine concentrations among healthy controls, cats with sepsis (n = 12) and cats with septic shock (n = 23) revealed that sick cats (sepsis or septic shock) had significantly higher plasma concentrations of IL-6, IL-8, KC-like, and RANTES compared to healthy controls." (PMID 32548135, 2020). "Inflammatory biomarkers, such as interleukin-6 (IL-6), neutrophil gelatinase-associated lipocalin (NGAL), and high-mobility group box 1 (HMGB1), have been effective at differentiating sepsis, predicting prognosis, and monitoring treatment in patients in the ICU." (PMID 32635454, 2020). "It was previously demonstrated that NAC + DFX decreased oxidative damage in this model of severe sepsis; thus, it was determined whether this protective effect was restricted to animals in the high IL-6 level group." (PMID 32401970, 2020).
Sepsis (continued). "Thus, it seemed that the sIL-6R blockade is overruled in situations with very high IL-6 production like severe sepsis." (PMID 32086584, 2020). "However, male KO mice had significantly higher levels of TNFα and IL-6 after sepsis when compared to male WT septic mice, while levels of IL-10 and KC were similar in both WT and KO male mice." (PMID 32117320, 2020). "A later study suggested that IL-6 may possibly have a role in sepsis diagnosis, as they noted elevated IL-6 concentrations in septic patients compared to controls." (PMID 32164268, 2020). "In addition, sepsis can activate the innate immune response and lead to a cytokine storm, most importantly in IL-1, IL-6, and TNF-α." (PMID 33317643, 2020). "Sepsis led to significant elevations in ET-1, IL-6, nitrotyrosine levels, and XOR activity." (PMID 33330526, 2020). "We aimed to conduct a prospective observational analysis to investigate the prognostic value of pentraxin 3, interleukin 6, procalcitonin, and lactate combined in predicting the 28-day mortality rate in patients with sepsis or septic shock (n = 160; sepsis, 78; sepsis shock, 82)." (PMID 32481464, 2020). "Comparisons of analyte concentrations among healthy controls, cats with sepsis and cats with septic shock revealed that sick cats (both with sepsis and septic shock) had significantly higher plasma concentrations of IL-6, IL-8, KC-like, and RANTES compared to healthy controls." (PMID 32548135, 2020). "In vivo and in vitro experiments also found that asiatic acid reduced the levels of inflammatory factors (IL-1β ↓, IL-6 ↓) by affecting the Notch signaling pathway, weakened liver and kidney damage, and improved the survival rate in the experimental sepsis mice model." (PMID 33013406, 2020). "Furthermore, the remarkably increased contents of IL‐6 and IL‐10 were observed in the circDNMT3B‐si group, compared with the sepsis group." (PMID 32383354, 2020). "For example, in a systemic inflammatory model of sepsis, IL-6 has been shown to be deleterious." (PMID 32310998, 2020). "Moreover, sepsis survivors showed a significant reduction in IL-6 levels at 6 h post ICU admission from the baseline levels." (PMID 32635454, 2020). "Inflammatory cytokines such as TNF-α and IL-6 result in cardiac dysfunction in sepsis." (PMID 31315617, 2019). "Trial sequential analysis showed that a large sample size was needed to get a more reliable result of the association between IL-6-174 G/C polymorphism and sepsis in non-adults." (PMID 30782124, 2019). "Serum IL-6 was also prominent in sepsis than ischemic models." (PMID 30991873, 2019). "Several proinflammatory cytokines, including IL-1ß, IL-6, and IL-17 were shown to be elevated in the serum of different inflammatory conditions such as sepsis, diabetes and rheumatoid arthritis and to induce enhanced NETosis of peripheral neutrophils in these disorders." (PMID 30967871, 2019). "For low-resource settings with high admission and infection rates in NICU, presepsin may be promising with higher sensitivity and similar cost with interleukin-6, which is routinely used with the aim of sepsis work-up in our clinic." (PMID 31387523, 2019). "After that, a meta-analysis in 2013 demonstrated that IL-6-174 G/C polymorphism did not have a link with the risk and mortality of sepsis at any age and ethnicity groups." (PMID 30782124, 2019). "Indeed a similar observation was made in a murine sepsis model, where plasma IL-6 levels 6 hours post infection predicted life or death." (PMID 31836803, 2019). "This correlation may be attributed to the fact that resistin is involved in the release of increased levels of pro-inflammatory biomarkers—IL-6, IL-12 and TNF-ɑ- that are involved in organ failure caused by sepsis." (PMID 30650128, 2019).
Sepsis (continued). "On the other hand, correlation analyses of the DNA methylation profiles in relation to IL-10 and IL-6 levels, which are increased in patients with sepsis, suggest a potential mechanism downstream to these cytokines participating in the defective generation of DNA methylation alterations." (PMID 31665078, 2019). "Il-6 is elevated in several hemolytic states and in mice studies to model human sepsis." (PMID 31554244, 2019). "The AUC of IL-6 to discriminate sepsis from the control group was 0.89 (95% confidence interval [CI], 0.97–1.00; P < 0.001), 0.84 for PTX3 (95% CI, 0.95–0.99; P < 0.001), 0.80 for PCT (95% CI, 0.86–0.96; P < 0.001), and 0.77 for CRP (95% CI, 0.71–0.91; P < 0.001)." (PMID 31718563, 2019). "The aim of this study was to evaluate whether Interleukin-6 (IL-6) could be a faster indicator of treatment success in adults with severe sepsis and septic shock compared to procalcitonin (PCT) and C-reactive protein (CRP)." (PMID 30760225, 2019). "Furthermore, blockade of IL-6 with a monoclonal antibody, in a primate model of sepsis, attenuated the LPS-induced coagulation." (PMID 31139194, 2019). "It is likely that similar types of inhibitors may be efficacious against inflammatory diseases where IL-6 is overproduced, such as sepsis and EAE." (PMID 31867000, 2019). "Among all variables measured, a combination of TEG-G (cut off value of <7 dynes/cm2) and IL-6 level (cut off value of >48 pg/dL) could best distinguish children with severe sepsis and +S/+NPMODS in our cohort." (PMID 31681719, 2019). "Interestingly, a model of acute I/R showed higher BUN and Scr at 24 h, but lower serum IL-6 in comparison with sepsis-AKI model." (PMID 30991873, 2019). "While there is a general consensus on the increase of PTX3 plasma levels in septic patients, and the correlation with severity from SIRS to sepsis and septic shock, the diagnostic superiority of PTX3 over other biomarkers, such as PCT, IL-6, CRP and lactate, is still under debate." (PMID 31031772, 2019). "Bacterial clearance in vivo may be associated in part to phagocytosis since sepsis-induced mice treated with MSC reduce inflammation (IL-10 and IL-6) while enhancing phagocytosis of S. aureus." (PMID 30975214, 2019). "In addition, elevations of IL-6 can be found in a variety of severe insults, such as trauma, burns, hemorrhagic shock, sepsis, and ischemia-reperfusion injuries together with IL-1 and TNF-α." (PMID 31336570, 2019). "This suggests that TSLP produced during sepsis increases IL-6 level, which may induce, at least in part, the changes in AST, ALT, and BUN levels." (PMID 31480519, 2019). "IL-6 alone or in combination with other inflammatory markers such as procalcitonin, C-reactive protein, and IL-10 has been shown to identify patients with sepsis in both children and neonates." (PMID 31681719, 2019). "Sepsis led to significant increase of IL-6 in RV compared to LV." (PMID 31247004, 2019). "In addition to CRP and PCT, interleukin-6 (IL-6) has been suggested as a biomarker in the context of critical illness and sepsis." (PMID 31569348, 2019). "IL6 is even proposed as a new biomarker for the diagnosis of sepsis, which might be helpful to provide adequate and timely management of critically ill patients and thus reduce the morbidity and mortality associated with this condition." (PMID 31780867, 2019). "Moreover, in severe sepsis model (cecum ligated for 1cm in CLP procedure), Ets2-deficient mice also showed increased IL-6 and TNF-α production in serum and poor survival." (PMID 31785145, 2019). "IL-6 is a key inflammatory mediator of sepsis that may alter intestinal barrier function by increasing expression of the keratin gene in intestinal epithelial cells." (PMID 31001563, 2019). "However, when IL-6 levels are sustained chronic inflammation occurs that can become life threatening, as in sepsis." (PMID 31554244, 2019).
Sepsis (continued). "DNA methylation profiles correlate with IL-10 and IL-6 levels, significantly increased in monocytes in sepsis, as well as with the Sequential Organ Failure Assessment score; the observed changes associate with TFs and pathways downstream to toll-like receptors and inflammatory cytokines." (PMID 31665078, 2019). "While IL-6 was hardly detectable in healthy controls (0.06 ± 0.04 ng/ml), sepsis patients within the first 24 h of diagnosis (referred to as day 0 here) had significantly increased IL-6 levels (0.84 ± 0.2 ng/ml), which declined slightly five days after diagnosis (0.61 ± 0.2 ng/ml)." (PMID 31086276, 2019). "Additionally, the excessive expression of inflammatory cytokines (TNF-α and IL-6) during sepsis leads to tissue and cell damage." (PMID 30779706, 2019). "Trial sequential analysis indicated that large sample size was needed to get a more reliable result for the association between IL-6-174 G/C polymorphism and the risk and mortality of sepsis in non-adults." (PMID 30782124, 2019). "Serum levels of TNF-α and IL-6 are indicative of the immune system activation during sepsis." (PMID 31747882, 2019). "This is in keeping with previous studies of major surgery and suggests that IL-6 may be the main driver of the postoperative response while TNF-α is involved in the inflammatory response to sepsis." (PMID 29454501, 2019). "However, under pathologic conditions such as sepsis, characterized by a massive cytokine release, including IL-6, the antioxidant defence is impaired suggesting an hormetic stress response to IL-6 cytokine." (PMID 31827671, 2019). "It is possible that, like in the murine cecal ligation puncture model of sepsis, specific blockade of IL-6 trans-signaling with sgp130Fc might be superior to global IL-6 blockade due to regenerative effects of IL-6 via the classic signaling pathway." (PMID 31694340, 2019). "One report, for example, compared induction of the IL-6 pro-inflammatory cytokine by cord blood monocytes following exposure to heat-killed GBS strains isolated from babies with sepsis or those who were asymptomatically colonized; enhanced IL-6 production was observed in response to sepsis isolates." (PMID 31536604, 2019). "Another prominent use of IL-6 as a biomarker is in sepsis or after major trauma." (PMID 31795299, 2019). "We identified significantly increased levels of IL-10 and IL-6 in patients with sepsis." (PMID 31665078, 2019). "The results did not present any association between IL-6-174 G/C polymorphism and the risk and mortality of sepsis." (PMID 30782124, 2019). "In canine studies modeling sepsis through injection of lipopolysaccharide (LPS), treated dogs had greater blood IL-6, IL-10, TNF-α, and KC-like concentrations up to 4-h post-injection and greater CCL2 up to 24-h post-injection, when compared to placebo-treated dogs." (PMID 31316998, 2019). "Taken together, the findings suggest that TSLP may be closely linked to a synergistic effect on IL-6 and AST levels during sepsis." (PMID 31480519, 2019). "Macrophages are one of the major early sources of TNFα, IL-6, and prostaglandins during sepsis." (PMID 31244655, 2019). "In accordance with organ dysfunction in the FtHfl/fl mice, 24 h after CLP surgery, there was a significant increase in the levels of cytokines that have been implicated in the pathogenesis of sepsis, including the pro-inflammatory cytokines, TNF-α, IFN-γ, IL-6, IL-12, CXCL1, IL-1β, and IL-2." (PMID 30804939, 2019). "In a rabbit model of experimental sepsis, presepsin was detected in the blood of the animals 2 h after surgery, peaked at 3 h, continued to increase for at least 5 h, and presepsin increased earlier than IL-6 and PCT." (PMID 31671729, 2019). "Another study reported that IL-6 exhibits superior kinetics when monitoring the effectiveness of antibiotic treatments and suggested that clinicians can use IL-6 as a prognostic marker in sepsis." (PMID 31718563, 2019).